RELN (reelin)
Diseases named in the same sentence as RELN in open-access papers (continued):
Sharing a sentence is not in itself a finding about the gene and the disease.
autism (continued). "In our study, reelin levels only from male children with autism tended to increase with age, suggesting the possibility of a different epigenetic mechanism with respect to female children with autism, and likely with respect to non-ASD children as well." (PMID 32292362, 2020). "Importantly, a study of the human temporal lobe found no change in the density of reelin-expressing neurons in autism: consistent with the findings reported here, this study further identified no change in neuron density in layer 1 in autism." (PMID 30867066, 2019). "Additionally, RELN, with almost no expression in NSCs and 2-fold greater expression levels in neurons vs. astrocytes, exhibited a highly significant 30-fold reduced expression in the astrocytes (but not in neurons) of patients with autism." (PMID 38994948, 2024).
Alzheimer disease (77 papers, 2006 to 2026). A progressive, neurodegenerative disease characterized by loss of function and death of nerve cells in several areas of the brain leading to loss of cognitive function such as memory and language. "The physiological dysfunction of Reelin has been implicated in the pathogenesis of several neurodegenerative diseases including epilepsy, depression, schizophrenia, and Alzheimer’s disease." (PMID 25790952, 2016). "Reelin is a signaling protein increasingly associated with the pathogenesis of Alzheimer’s disease that relevantly modulates tau phosphorylation." (PMID 23951306, 2013). "In the brain, reduced reln expression or reelin signalling activity is implicated in the generation of Alzheimer's disease." (PMID 20027296, 2009). "Notably, similar Reelin processing changes have been implicated in synaptic dysfunction and neurodegeneration in Alzheimer’s disease, suggesting a possible convergent pathological mechanism." (PMID 40733546, 2025). "Reelin expression in the central nervous system (CNS) has been implicated in a wide range of neurodegenerative diseases, such as Alzheimer’s disease (AD), cognitive disorders, such as autism spectrum disorder, and neuropsychiatric disorders, such as schizophrenia and bipolar disorder." (PMID 38607022, 2024). "Reelin deficiency can change fear learning when comorbid with Alzheimer’s disease risk factors." (PMID 38137152, 2023). "Amyloid beta precursor protein (APP), while frequently implicated in Alzheimer's disease (AD) and relating to the formation of amyloid plaques, may also interact with reelin and modulate synaptic plasticity." (PMID 30498460, 2018). "Finally, recent studies point to the participation of Reelin in Alzheimer’s disease and in the synaptopathies associated with this condition." (PMID 27303269, 2016). "Interestingly, there are numerous connections between the components of the Reelin signaling pathway and molecules that have been implicated in Alzheimer's disease (AD)." (PMID 22355340, 2012). "Also, the inactivation of Reelin by ADAMTS2 may be a pathogenic process since reduced Reelin levels were linked with worse Alzheimer's disease pathology in animal models." (PMID 40837410, 2025). "Prion infection further disrupted the Reelin signaling pathway, thus downregulating Dab1 and Reelin receptors and altering Reelin processing, like Alzheimer’s disease pathology." (PMID 40733546, 2025). "We identify vulnerable populations of excitatory and inhibitory neurons that are depleted in specific brain regions in Alzheimer’s disease, and provide evidence that the Reelin signalling pathway is involved in modulating the vulnerability of these neurons." (PMID 39048816, 2024). "APOER2 is a type I transmembrane receptor that interacts with extracellular ligands, notably the neuroprotective Reelin and APOE, a risk factor associated with Alzheimer’s disease (AD)." (PMID 39038048, 2024). "Reduction of the reelin level by ADAMTS-4 and ADAMTS-5-dependent degradation is associated with hyperphosphorylated tau protein, forming neurofibrillary tangles leading to Alzheimer’s disease." (PMID 38980840, 2024). "The EC is one of the first regions of the brain to be affected in Alzheimer’s disease, and previous work has linked cognitive decline to the loss of LAMP5+RELN+ cells." (PMID 38122823, 2024). "Regarding neurodegeneration, murine models of Alzheimer’s disease (AD) show an early decline of Reelin in the hippocampus and cortex, and human brains of AD patients have lower Reelin levels." (PMID 39062513, 2024). "Case report of an individual heterozygous for a rare RELN-COLBOS variant that confers resilience, via a gain-of-function mechanism, to Alzheimer’s disease." (PMID 37188781, 2023). "In prodromal Alzheimer’s disease, these reelin-expressing neurons are prone to accumulate intracellular amyloid-β, which is mimicked in a rat model that replicates the spatio-temporal cascade of the disease." (PMID 37091586, 2023).
Alzheimer disease (continued). "In support of Reelin’s potential involvement in AD, three polymorphisms of variants in the RELN gene (loss of function) have been associated with Alzheimer’s disease." (PMID 37891846, 2023). "Reelin depletion is regarded as an early phenomenon in Alzheimer’s disease, whereas clusterin promotes amyloid beta clearance." (PMID 35457118, 2022). "As recently shown, SP-C is entangled in characteristic neuropathological changes in a murine model of Alzheimer’s disease (AD), represented by Reelin/SP-C double-positive deposits that manifest in an age-dependent fashion." (PMID 35053244, 2022). "Recent studies have revealed the ability of VLDLR to interact with multiple ligands and molecules such as reelin and clusterin, which are correlated with Alzheimer’s disease." (PMID 35457118, 2022). "Differences in reelin complexes have been reported in other neurological condition such as Alzheimer’s disease." (PMID 32292362, 2020). "Decreased levels of Reelin activity have been postulated as a key factor during neurodegeneration in Alzheimer’s disease (AD) and in aging." (PMID 32438605, 2020). "An increased processing of Reelin was found in patients suffering from frontotemporal dementia, Alzheimer’s disease or Down syndrome." (PMID 32604886, 2020). "In addition, isoforms E2 and E4 have been shown to promote atherosclerosis via Reelin by increasing vascular inflammation, thereby increasing the risk for cerebrovascular and cardiovascular pathologies as well as neurological pathologies, specifically Alzheimer’s disease." (PMID 30622122, 2019). "There are few lines of evidence that Reelin is involved in or even has a protective role against development of Alzheimer’s disease (AD)." (PMID 30304853, 2018). "In a transgenic Alzheimer’s disease mouse model, reduction in Reelin-mediated signaling leads to elevated amyloidogenic APP processing and amyloid-β deposition." (PMID 30304853, 2018). "Reelin expression and glycosylation patterns are altered in the frontal cortex and cerebellum of Alzheimer’s disease patients." (PMID 25790952, 2016). "Others show an increased cerebrospinal RELN concentration in patients with Alzheimers disease and Frontotemporal Dementia." (PMID 26305216, 2015). "Reductions in Reelin levels have been suggested to contribute to Alzheimer’s disease (AD) pathophysiology." (PMID 24252415, 2013). "Increasing evidence suggests that Reelin expression is altered in the Alzheimer’s disease (AD) brain." (PMID 23951306, 2013). "The 50-gene set is based on the manual selection of genes related to cancer biology, Alzheimer's disease and development, and includes 5 genes that are involved in the Reelin pathway." (PMID 16438716, 2006). "The second contains 50 genes related to cancer biology, Alzheimer's disease and development (referred to as the Reelin dataset)." (PMID 16438716, 2006). "Further studies on Reelin signaling are needed to clarify its precise role in Alzheimer’s disease." (PMID 39468007, 2024). "This study assesses whether reelin proteolytic fragments are differentially affected in the cerebrospinal fluid (CSF) of Alzheimer’s disease (AD) subjects." (PMID 35886870, 2022). "Indeed, the level changes of Reelin in biological fluids (i.e., cerebrospinal fluid (CSF)) have been analyzed by several groups during neurodegeneration (typically Alzheimer’s disease (AD)) and aging." (PMID 32438605, 2020). "Also, the glycosylation pattern of Reelin in the cerebrospinal fluid of Alzheimer disease patients seems to be altered." (PMID 30304853, 2018).
Alzheimer disease (continued). "Direct support for this idea comes from observations that reelin overexpressing mice have increased neurogenesis and that exogenous reelin can recover cognitive deficits in mouse models of both Angelman syndrome and Alzheimers Disease." (PMID 29515447, 2018). "Interestingly knockdown of Reelin, the glycoprotein absent in reeler mutant mice, impairs rats in the object recognition task, whereas Reelin overexpression can rescue deficits in the object recognition task in mouse models of Alzheimer's disease." (PMID 28550099, 2017). "Support for the dysfunction of Reelin proteolysis in neurodegeneration and cognitive dysfunction comes from postmortem analysis of Alzheimer’s diseases (AD) tissues including cerebral spinal fluid (CSF), showing that levels of Reelin fragments are altered in AD compared to control." (PMID 27065802, 2016). "Moreover, infusion of Reelin enhances cognitive performance in wild-type mice, while overexpression fully rescues cognitive deficits in mouse models of Alzheimer’s disease and during normal aging." (PMID 27303269, 2016). "Furthermore, Reelin signal transduction pathways appear to be particularly vulnerable in Alzheimer’s disease (AD), potentially contributing to its pathogenesis." (PMID 27065802, 2016). "In frontal cortex extracts an increase in Reelin mRNA, and in soluble and insoluble (guanidine-extractable) Reelin protein, was associated with late Braak stages of Alzheimer’s disease (AD), while expression of its receptor, ApoER2, did not change." (PMID 27531658, 2016). "It has been shown that proteolytic processing of Reelin decreases its signaling activity and promotes Reelin aggregation in vitro, and that proteolytic processing is affected in various neurological disorders, including Alzheimer's disease (AD)." (PMID 23082219, 2012). "Reducing the Reelin gene dose augments Aβ plaque formation in a mouse model of Alzheimer's disease." (PMID 22355340, 2012). "Recent findings highlight that Reelin, a glycoprotein involved in neural development, synaptic plasticity, and neuroinflammation, plays some specific roles in neurodegenerative disorders associated with aging, such as age-related macular degeneration (AMD) and Alzheimer’s disease (AD)." (PMID 40806482, 2025). "This interaction elicits an increase in Reelin expression in cells, but decreases the internalization of ApoER2 from the cytoplasmic membrane; thus Aβ hinders Reelin biological activity and ultimately could influence pathological progression of Alzheimer’s disease by impairing Reelin signaling." (PMID 27531658, 2016). "Further understanding of PC development may elucidate etiologies and predict potential treatment strategies for neuronal migration disorders such as Lissencephaly and Zellweger syndrome as well as in Reelin signaling-involved neurodegenerative diseases such as Alzheimer’s disease." (PMID 24828132, 2015). "Between RELN and NOS1, three exons are altered in their expressions in the human hippocampus affected by Alzheimer’s disease." (PMID 30704480, 2019). "Altered expression patterns (exon skipping events) within two distinct exon regions of RELN and NOS1 in the human hippocampus affected by Alzheimer’s disease (AD) were identified." (PMID 30704480, 2019). "Since Reelin and apolipoprotein E, are ligands of ApoER2 and VLDLR, these receptors are of interest with respect to Alzheimer’s disease." (PMID 30304853, 2018). "Restoring the delicate balance of various Reelin fragments in the brain may offer convergent therapeutic avenues to stabilize synaptic and immune function in conditions spanning ASD to Alzheimer's disease." (PMID 41416042, 2025). "The results of our analysis clearly show that, although the Reelin pathway genes are clustered together with some known Alzheimer's disease genes, they are not the only ones that share semantic features with Alzheimer's-disease-associated genes." (PMID 16438716, 2006).
Alzheimer disease (continued). "There is also a chance that Reelin signaling dysregulation occurs at an early stage in ASD and that the increased levels are due to a compensatory mechanism to a Reelin-resistant state, similar to what might be occurring with respect to Alzheimer’s disease." (PMID 37891846, 2023). "Next, we assessed the transcriptome of genes of interest to Alzheimer’s disease and resistance, APOE, APP, MAPT, PSEN1, and RELN and found no notable differences across cell lines." (PMID 38571814, 2024). "The biological significance of the Reelin/APP interaction is not yet elucidated but, during the last few years, accumulating evidence has suggested the involvement of Reelin in the pathogenesis of Alzheimer’s disease." (PMID 25418135, 2015).
depression (65 papers, 2010 to 2025). "All these studies support the dysregulation of reelin to be associated with an epigenetic mechanism in several psychiatric disorders that have many commonalities with depression." (PMID 35203405, 2022). "We found that the timecourse for the emergence of depression-like behavior after corticosterone administration parallels the timecourse for dampened neurogenesis and the loss of reelin-positive cells." (PMID 30804748, 2019). "If alterations in hippocampal reelin are involved in depression, we would expect to see a loss of reelin-positive cells in rats subjected to the CORT injections but not restraint stress." (PMID 26941609, 2016). "To assess potential mechanisms underlying the fast-acting antidepressant actions of ketamine we used a repeated corticosterone paradigm in adult male rats to assess the effects of ketamine on reelin-positive cells, a protein largely implicated in the pathophysiology of depression." (PMID 32982757, 2020). "Importantly, this work also implicated the extracellular matrix protein reelin in the pathogenesis of depression." (PMID 29928190, 2018). "We have previously hypothesized about the important role that reelin could play in the neurobiology of depression, as revealed by our observations that depression-like behavior is associated with a significant decrease in the number of reelin+ cells in the subgranular zone." (PMID 30804748, 2019). "This suggests that the pattern of behaviors (e.g., depression-like behavior, impaired cognition) observed under times of increased inflammatory signaling in chronic stress might be related to a loss of hippocampal reelin expression." (PMID 29515447, 2018). "Moreover, these authors exposed heterozygous reeler mice to increasing concentrations of corticosterone for 21 days, which caused an increase in depression-like behaviors, decreases in Reelin expression and in hippocampal neurogenesis, all with cell maturation impairments." (PMID 25679528, 2015). "Reelin, an endogenous glycoprotein downregulated in depression, has shown rapid antidepressant-like effects akin to those of the N-methyl-D-aspartate receptor (NMDAR) antagonist ketamine." (PMID 41257792, 2025). "For example, exposure to Sn decreased the level of reelin protein expression within the hippocampus of rats, possibly leading to depression." (PMID 40624645, 2025). "Reelin provides a novel avenue for research into therapy for depression as it has fast antidepressant effects that operate through mechanisms distinct from most currently used antidepressants." (PMID 38255890, 2024). "In light of these investigations, it is plausible that reelin is involved in the progression of many of the gut abnormalities observed in depression, and that there is a cyclic nature to these disruptions." (PMID 38255890, 2024). "Reelin brain expression is downregulated in mood and psychotic disorders, and reelin injections have fast antidepressant-like effects in animal models of depression." (PMID 38255890, 2024). "Genetic deletion- or chronic stress exposure-induced Reelin reduction in the hippocampus has been reported to exhibit suppressed synaptic plasticity and increased depression-like behavior and cognitive deficits." (PMID 39339187, 2024). "The results shown here demonstrate that Reelin has antidepressant-like effects in a rodent model of recurring depression." (PMID 38482060, 2024). "The extracellular matrix (ECM) protein reelin is downregulated in central and peripheral structures in depression, and its levels are restored with the administration of antidepressants." (PMID 38255890, 2024).